TRPV5 (transient receptor potential cation channel subfamily V member 5)
Description:
Constitutively active calcium selective cation channel thought to be involved in Ca(2+) reabsorption in kidney and intestine. Required for normal Ca(2+) reabsorption in the kidney distal convoluted tubules (By similarity). The channel is activated by low internal calcium level and the current exhibits an inward rectification. A Ca(2+)-dependent feedback regulation includes fast channel inactivation and slow current decay (By similarity). Heteromeric assembly with TRPV6 seems to modify channel properties. TRPV5-TRPV6 heteromultimeric concatemers exhibit voltage-dependent gating (By similarity).
Synonyms: CaT2; ECaC1; OTRPC3
Tractability: Small molecule: it belongs to a druggable protein family. Antibody: UniProt places it where antibodies can reach, with high confidence; its Gene Ontology location is reachable by antibodies, with high confidence; UniProt predicts a signal peptide or a membrane-spanning region. PROTAC: a small molecule that binds it is known.
Target class: Voltage-gated ion channel; Ion channel; Transient receptor potential channel
Gene: Protein-coding gene on chromosome 7 (142,908,101 to 142,933,746, reverse strand). Ensembl gene ENSG00000127412.
Subcellular location: Apical cell membrane
Pathways (Reactome):
Transport of small molecules: TRP channels
Gene Ontology:
Molecular function: calcium channel activity; protein binding; monoatomic ion channel activity
Biological process: calcium ion import across plasma membrane; calcium ion transmembrane transport; calcium ion homeostasis; calcium ion transport; protein homotetramerization; regulation of urine volume; calcium ion transport into cytosol; monoatomic ion transport; transmembrane transport
Cellular component: apical plasma membrane; plasma membrane; calcium channel complex; membrane
Genetic constraint (gnomAD): Loss-of-function variants: 62 observed, 76.04 expected, observed/expected ratio (o/e) 0.82, 90% interval 0.66 to 1.01. The upper end of that interval is the gene's LOEUF score, 1.01, which puts it in group 4 of 6, group 1 being the genes least tolerant of losing a copy. Missense variants: 889 observed, 934.92 expected, observed/expected ratio (o/e) 0.95, 90% interval 0.9 to 1. Synonymous variants: 377 observed, 361.64 expected, observed/expected ratio (o/e) 1.04, 90% interval 0.96 to 1.13.
Homologues: Orthologues: chimpanzee TRPV5 (98% identical), macaque TRPV5 (97% identical), dog TRPV5 (87% identical), rabbit TRPV5 (84% identical), pig TRPV5 (83% identical), guinea pig TRPV5 (81% identical), mouse Trpv5 (81% identical), rat Trpv5 (80% identical), Caenorhabditis elegans ocr-4 (24% identical), Drosophila melanogaster iav (24% identical), Drosophila melanogaster nan (24% identical), Caenorhabditis elegans osm-9 (21% identical). Paralogues in human: TRPV6 (74% identical), TRPV4 (29% identical), TRPV1 (28% identical), TRPV2 (25% identical), TRPV3 (25% identical).
Diseases named in the same sentence as TRPV5 in open-access papers:
TRPV5 is named in the same sentence as 63 diseases in open-access papers, as found by Europe PMC text mining. Sharing a sentence is not in itself a finding about the gene and the disease. The quoted sentences say what the papers report.
Hypercalciuria (27 papers, 2007 to 2025). "Previous searches for TRPV5 variants have largely examined cases of hypercalciuria or kidney stone formers with a likely autosomal dominant inheritance." (PMID 38839989, 2024). "Herein, using a combination of homozygosity mapping and WES, we describe the homozygous missense variant (c.1792G>A; p.(Val598Met)) in TRPV5 that causes renal Ca2+-wasting hypercalciuria (RCWH)." (PMID 38528055, 2024). "Taken together, our data demonstrate that biallelic TRPV5 mutations are responsible for a novel form of monogenic hypercalciuria in humans, which we term renal calcium-wasting hypercalciuria (RCWH)." (PMID 38528055, 2024). "In mice, TRPV5 knockdown altered renal calcium handling which led to diminished active calcium reabsorption and thus produced severe hypercalciuria; the latter is a major risk factor for kidney stone formation." (PMID 36088585, 2022). "The close homology and sequence similarity between TRPV6 and TRPV5 suggest that these approaches can also be extended to TRPV5-linked diseases, including hypercalciuria, nephrolithiasis, and bone disorders." (PMID 34725357, 2021). "Tg6 mice had mild hypercalciuria which is probably caused by the downregulation of TRPV5 calcium channels and calbindin D28k, both expressed in the distal convoluted tubule and connecting tubule, the last nephron segment capable of calcium reabsorption." (PMID 31628396, 2019). "Limited clinical studies about the association between TRPV5 genotypes and hypercalciuria are available." (PMID 26089600, 2015). "In TRPV5−/− mice, Renkema and coworkers demonstrated that the risk of supersaturation produced by hypercalciuria is attenuated by activation of apical CaR, resulting in reduced AQP2 expression and higher net acid secretion though H+-ATPase." (PMID 22403735, 2012). "Therefore, it is likely that these additional bone phenotypes are due to the somatic GNAS variant, while the germline TRPV5 variant causes hypercalciuria." (PMID 38839989, 2024). "The current case and studies of the Trpv5 knockout mouse and its heterozygous littermates indicate that a loss of functional channel may be required on both alleles for hypercalciuria with normal PTH to be present." (PMID 38839989, 2024). "In addition, several human TRPV5 variants have been associated with hypercalciuria and nephrolithiasis in case-control studies." (PMID 38528055, 2024). "TRPV5 down-regulation could decrease calcium reabsorption and exaggerate its urinary excretion leading to hypercalciuria which per se is a recognizable risk factor in stone formation." (PMID 36088585, 2022). "Available evidence suggests that downregulated TRPV5 expression may be a vital pathogenic factor in the formation of hypercalciuria and Ca2+-containing nephrolithiasis." (PMID 35251369, 2022). "Moreover, while the variant was only found in a single hypercalciuric family, further studies of other consanguineous families with idiopathic hypercalciuria may provide more evidence that pathogenic TRPV5 variants contribute to human disease." (PMID 38839989, 2024). "Thus, investigation of hypercalciuria or kidney stone disease in consanguineous families may yield more variants in the TRPV5 gene." (PMID 38839989, 2024). "However, Nijenhuis et al23 found that TRPV5 knock‐out mice developed severe hypercalciuria and reduced bone thickness, implicated that TRPV5 may has an inhibitory effect on the process of bone resorption." (PMID 30063124, 2018). "A previous study indicated that a TRPV5 genetic polymorphism has a conservative calcium effect in African subjects, and an animal model showed that genetic knockdown in mice produced serious hypercalciuria, which is a major risk factor for kidney-stone formation." (PMID 26089600, 2015). "The difference is hormonal response between Cldn16 KO and Trpv5 KO mouse models can account for different activation levels of CaSR in the collecting duct, therefore resulting in the different responses to hypercalciuria." (PMID 38339056, 2024).
Hypercalciuria (continued). "The importance of TRPV5 is evidenced by Trpv5 knockout mice, which present with severe hypercalciuria, together with bone abnormalities, significantly higher levels of 1,25‐dihydroxyvitamin D3 and compensatory intestinal Ca2+ hyperabsorption." (PMID 39576090, 2024). "Trpv5-knockout mice (Trpv5−/−) present with marked hypercalciuria as a result of renal Ca2+ wasting, which is compensated by an increase of 1,25-dihydroxy vitamin D3 leading to normocalcemia." (PMID 38528055, 2024). "However, there is some evidence that point mutations may contribute to hypercalciuria, as heterozygous mice with the ENU-induced TRPV5 p.(Ser682Pro) variant have hypercalciuria and hyperphosphaturia, similar to the family described with the p.(Val598Met) variant." (PMID 38839989, 2024). "The importance of TRPV5 in Ca2+ homeostasis is exemplified in Trpv5 knockout mice, which exhibit reduced renal Ca2+ reabsorption leading to hypercalciuria-induced polyuria coupled with urine acidification." (PMID 33718388, 2021). "This is exemplified by TRPV5 knock out mice, which have been reported to have systemic calcium imbalance in the form of hypercalciuria and bone mineral loss." (PMID 30305626, 2018). "In Trpv5−/− mice, besides hypercalciuria, intestinal Ca2+ hyperabsorption takes place by upregulation of the close homolog of Trpv5, Trpv6." (PMID 27102152, 2016). "Animal models demonstrated the functional roles of the transient receptor potential vanilloid member 5 (TRPV5) gene in calcium renal reabsorption and hypercalciuria." (PMID 26089600, 2015). "AQP2 was also reduced in the inner medulla of animal models of hypercalciuria including hypercalciuric rats and TRPV5 null mice." (PMID 25006961, 2014). "The further increase in hypercalciuria in Trpv5682P/682P mice compared to Trpv5682P/+ mice is likely due to the active TRPV5 channel consisting of four TRPV5 monomers that form a central pore _ENREF_34." (PMID 23383183, 2013). "Alterations in the calcium channel transient receptor potential cation channel subfamily V member 5 (TRPV5) and the glycoprotein mucin-1 (MUC1) have been associated with both hypercalciuria, which predisposes individuals to kidney stones, and tumor progression." (PMID 41182764, 2025). "Therefore, the identification of a biallelic inactivating TRPV5 variant p.(Val598Met) in multiple affected members of a family provides the first convincing evidence that TRPV5 contributes to monogenic hypercalciuria." (PMID 38839989, 2024). "On the other hand, the virtual Hypercalciuria/Hyper-PTH panel uncovered only the TRPV5 variant, but this variant being not unique to the proband, cannot explain his severe skeletal phenotype." (PMID 38528055, 2024). "Since CaSR is suggested to promote urine acidification and diuretic effects in response to hypercalciuria in Trpv5 KO mice, changes in the activation level of this receptor due to changes in hormonal response can lead to different overall responses in Cldn16 KO mice." (PMID 38339056, 2024). "Likewise, whereas Trpv5 KO mice showed hypercalciuria only, Cldn16 KO mice showed hypercalciuria accompanied by hypermagnesuria." (PMID 38339056, 2024). "On the other hand, TRPV5 null mice present less severe physiological consequences, nonetheless, the absence of TRPV5 channels causes hypercalciuria, compensatory hyperabsorption of dietary calcium, and abnormal bone thickness." (PMID 32457384, 2020). "Hypercalciuria, polyuria, and urinary acidification occurred in TRPV5‐null (TRPV5−/−) mice’ renal." (PMID 30666830, 2019). "Investigating TRPV5 modulation with cryo-EM permitted us to gain insight regarding TRPV5 gating and potentially form the basis for rational drug design for the treatment and prevention of hypercalciuria and nephrolithiasis in future studies." (PMID 30305626, 2018). "On the contrary, TRPV5 KO mice are viable but present with severe hypercalciuria." (PMID 27101128, 2016).
Hypercalciuria (continued). "Previous study found that mice lacking TRPV5 exhibited reduced calcium reabsorption, which caused severe hypercalciuria." (PMID 24093218, 2013). "In addition, the HCALC1 mouse established by this study provides a pre-clinical model to evaluate treatments (e.g. diet or drugs) for hypercalciuria as well as facilitating studies of the physiological role of TRPV5 in renal calcium excretion." (PMID 23383183, 2013). "Pseudohypoaldosteronism (PHA) type II from with-no-lysine kinase 4 (WNK-4) mutation can cause hypercalciuria from its role in regulation of TRPV5, whereas dRTA leads to hypercalciuria indirectly from metabolic acidosis and increased bone resorption." (PMID 17464515, 2007). "Thus, the hypercalciuria is a consequence of the TRPV5 mutation, but not the GNAS mutation, in the proband." (PMID 38528055, 2024). "In our opinion, hypercalciuria may be partly caused by sKL reduction, as lack of this molecule diminishes the activity of TRPV5 channels and leads to increased renal calcium excretion although we did not observe significant association between the degree of calciuria and magnitude of sKL reduction." (PMID 28130714, 2017). "FGFR1 effects to diminish membrane expression of TRPV5 in Fgfr1DT-cKO mice likely accounts for both the inability of PTH and intracellular calcium transport pathways to compensate for the hypercalciuria." (PMID 26839958, 2016). "On the other hand, the heterozygous mice (Trpv5 + /−) do not have any significant hypercalciuria compared to wildtypes, which is in line with our observations that only show an insignificant reduction of TRPV5 function in double-transfected HEK293 cells." (PMID 38528055, 2024). "For example, TRPV5−/−knockout mice demonstrated robust hypercalciuria and hyperphosphaturia without calcium-phosphate stone precipitation." (PMID 31754202, 2019). "Another report with 20 French hypercalciuria patients found nonsignificant functional impacts of three TRPV5 SNPs (A8V, R154H, and A561T) compared to wild-type normal TRPV5." (PMID 26089600, 2015). "However, studies in human populations have, to date, been disappointing, with targeted sequencing of TRPV5 in families with hypercalciuria identifying no significant findings." (PMID 38839989, 2024). "Thus, our findings indicate that the TRPV5 S682P mutant is functionally significant and study of HCALC1, a novel model for autosomal dominant hypercalciuria, may help further our understanding of renal calcium reabsorption and hypercalciuria." (PMID 23383183, 2013).
kidney stones (14 papers, 2015 to 2025). "Rare missense mutations in the TRPV5 gene have been reported to be associated with recurrent kidney stones." (PMID 40924792, 2025). "Due to the vital role of TRPV5 in calcium reabsorption, associations between variants in the gene and renal hypercalciuria and kidney stone formation have been sought since the channel’s discovery twenty-five years ago." (PMID 38839989, 2024). "Among those, we found rare missense variants at highly conserved sites in SLC34A1 and TRPV5 associating strongly with risk of kidney stones and recurrent kidney stones." (PMID 26272126, 2015). "In summary, despite the complexity of nephrolithiasis and the potential association of numerous calcium homeostatic absorption/reabsorption factors, TRPV5 plays an important role in the pathogenesis of calcium nephrolithiasis." (PMID 26089600, 2015). "We recruited 365 nephrolithiasis patients to conduct an association study between the TRPV5 genetic polymorphism, rs4236480, and stone multiplicity/recurrence in calcium nephrolithiasis patients." (PMID 26089600, 2015). "The mother (individual I-2) had nephrolithiasis during her fifth pregnancy at 25 years of age, presumptively suggesting that heterozygosity for the TRPV5 variant may be a predisposing factor for nephrolithiasis." (PMID 38528055, 2024). "However, in a large case-control study from Iceland, the rare missense TRPV5 variant (rs757494578, c.1589T>G; p.(Leu530Arg)) was associated with recurrent kidney stones." (PMID 38528055, 2024). "Focusing our analysis on coding sequence variants in 63 genes with preferential kidney expression we identify two rare missense variants SLC34A1 p.Tyr489Cys (OR=2.38, P=2.8 × 10−5) and TRPV5 p.Leu530Arg (OR=3.62, P=4.1 × 10−5) associating with recurrent kidney stones." (PMID 26272126, 2015). "In addition to SLC34A1 p.Tyr489Cys, we found a rare missense variant in TRPV5 (NP_062815.2:p.Leu530Arg (MAF=0.13 %) associating significantly with recurrent kidney stones (OR=3.62, P=4.1 × 10−5<0.05/220=2.3 × 10−4)." (PMID 26272126, 2015). "However, whether genetic polymorphisms of TRPV5 are associated with kidney stone multiplicity or recurrence is unclear." (PMID 26089600, 2015). "A significant role in nephrolithiasis predisposition is mediated by CASR and TRPV5 (epithelial calcium channel transient receptor) a long-standing candidate gene for KSD and hypercalciuria." (PMID 40786091, 2025). "For instance, a recent study confirmed that UMOD prevents the formation of kidney stones by stimulating Ca2+ reabsorption via TRPV5." (PMID 35251369, 2022). "Due to its role in calcium handling, potent and specific chemical modulators of TRPV5 have the potential to aid in treatments of calcium homeostasis disorders such as nephrolithiasis and hypercalcemia." (PMID 31647410, 2019). "Moreover, significant associations were reported between the non-synonymous single nucleotide polymorphism (SNP) rs4236480 of the TRPV5 gene and the risk of KSD in a West Bengal population of India and with kidney stone multiplicity in Taiwanese patients." (PMID 36088585, 2022). "In our study, interestingly, we verified the molecular mechanism of miR-103a-3p in kidney stones that miR-103a-3p silencing could alleviate oxalate-induced injury in NRK-52E cells by activating the UMOD/TRPV5 axis." (PMID 35251369, 2022). "Interestingly, the calcium channel TRPV5 has been the focus of several studies suggesting a role in kidney stone formation." (PMID 26272126, 2015). "The lack of potent, specific modulators of TRPV5 has limited the ability to probe the contribution of TRPV5 in disease phenotypes such as hypercalcemia and nephrolithiasis." (PMID 31647410, 2019). "All these findings suggested that UMOD could interact with TRPV5 in the formation of kidney stones, which has not been borne out yet." (PMID 35251369, 2022).
osteoarthritis (5 papers, 2023 to 2025). A noninflammatory degenerative joint disease occurring chiefly in older persons, characterized by degeneration of the articular cartilage, hypertrophy of bone at the margins and changes in the synovial membrane. "The MAPK pathway, which has been reported to be activated by TRPV5-regulated P-CaMKII, also plays a critical role in cell apoptosis in osteoarthritis development." (PMID 40845591, 2025). "A previous study reported the involvement of TRPV5 in inflammatory regulation under pathological conditions like osteoarthritis." (PMID 40708193, 2025). "Prior research has reported TRPV5 upregulation in a rat osteoarthritis model, in which TRPV5 induces chondrocyte apoptosis via the mitogen‐activated protein kinase cascade and the AKT/mechanistic target of the rapamycin pathway in osteoarthritis." (PMID 40708193, 2025). "For instance, blocking TRPV5 reduces inflammatory cytokine expression in osteoarthritis patient‐derived chondrocytes, indicating a potential role for TRPV5 in modulating inflammatory responses under pathological conditions." (PMID 40708193, 2025). "TRPV5 is expressed in chondrocytes and upregulated during the progression of osteoarthritis." (PMID 37198647, 2023).
renal cell carcinoma (5 papers, 2014 to 2023). "An altered vitamin D receptor expression may be associated with renal cell carcinoma carcinogenesis via TRPV5/6." (PMID 37892239, 2023). "Altered TRPV5 expression has been identified among the different renal cell carcinoma histopathological subtypes." (PMID 37892239, 2023). "A previous study reported that TRPV5/6 expression was remarkably decreased in human renal cell carcinoma compared with normal kidney tissues." (PMID 35558077, 2022). "In addition, vitamin D receptor overexpression could inhibit proliferation, migration, and invasion of renal cell carcinoma cells by increasing TRPV5 expression." (PMID 35558077, 2022).